Y_RNA (Y RNA )
Gene: Miscellaneous RNA gene on chromosome 14 (88,840,165 to 88,840,263, forward strand). Ensembl gene ENSG00000207342.
Homologues: Orthologues: chimpanzee Y_RNA (90% identical), macaque Y_RNA (87% identical). Paralogues in human: Y_RNA (89% identical), Y_RNA (88% identical), RNY3 (87% identical), Y_RNA (87% identical), RNY3P1 (86% identical), Y_RNA (86% identical), RNY3P14 (85% identical), RNY3P4 (85% identical), Y_RNA (85% identical), Y_RNA (84% identical), RNY3P11 (83% identical), RNY3P16 (83% identical), and 96 more.